GPX1 (glutathione peroxidase 1)
Diseases named in the same sentence as GPX1 in open-access papers (continued):
Sharing a sentence is not in itself a finding about the gene and the disease.
tumor (continued). "In summary, while PPARA, VDR, SLC16A1 and PAPSS2 supply the building blocks to synthesize macromolecules, GPX1 provides redox defense to counteract oxidative stress produced as a consequence of the high proliferation rates of tumor cells." (PMID 35565211, 2022). "Several of the most highly induced genes, CHI3L1, GPX1, PLIN1, PLIN4, and JAK3, have been linked to enhanced growth or cell survival in other tumor types." (PMID 35787784, 2022). "Pancreatic ductal adenocarcinoma cells can induce protective autophagy via the activation of ROS/AMPK signaling and GPX1 degradation to survive in a glucose-starved tumor microenvironment." (PMID 35626163, 2022). "In freshly isolated hepatocellular carcinoma tissues, decreased expression of selenium-binding protein 1 promotes tumor vascular invasion by increasing GPX1 activity." (PMID 35626163, 2022). "From previous studies and our study, we noted that GPX1 functions with different behaviors based on the tumor type." (PMID 34943522, 2021). "Knockdown of GPx1 reduced proliferation and activated apoptosis, with the VPS9D1 antisense RNA 1 acting as a tumour promoter to increase GPx1 expression and decrease miR-491-5p and miR-214-3p." (PMID 34679751, 2021). "Most studies suggest that high expression of GPX1 in tumor tissue is correlated with worse survival." (PMID 34200699, 2021). "GPx1 expression is decreased in many tumor types and its overexpression, both in vitro and in vivo, has been found to reduce the growth of cancer cells and carry out a protective role." (PMID 32426284, 2020). "Bioinformatics analysis found that high expression of GPX1 was positively correlated with tumor stage, distant metastasis and lymphatic metastasis." (PMID 31844035, 2019). "A significant correlation has been observed between GPX1 expression and T-stage as well as index tumor sites in HNSCC patients." (PMID 31824853, 2019). "GPX1 has been reported to be involved in both pro- and anticancer effects in different tumor models." (PMID 31844035, 2019). "Regarding the SELENOP level, TXNRD2 and TXNRD3 tumor tissue expression was negatively correlated (p = 0.037 and 0.045), while GPX1 had a higher expression in the normal tissue, p = 0.034." (PMID 30469315, 2018). "Next, these peptide-cluster compounds were chemically synthesized and their suppression activities were verified by studying GPx-1 activity in buffer solution and tumor cells, respectively." (PMID 28273930, 2017). "Glutathione peroxidase-1 (GPx-1), a crucial antioxidant selenoenzyme in mammalian cells, is selected as a model drug target for tumor treatment." (PMID 28273930, 2017). "In the present study the aldo-keto reductases AKR1C14, AKR1C18 and AKR1C6 were uniquely expressed in tumours, however glutathione peroxidase 1 was repressed to 30% of healthy control livers to possibly support HIF-1 signalling." (PMID 25872475, 2015). "GPX1 expression was associated with the Laurence type and WHO classification of tumor subtypes, but the mechanism is unclear." (PMID 24228025, 2013). "Based on our analysis of gene PARTP, GPX1, GPX3, and SELS were associated with ER-/PR+ tumor status, while SELS was also associated with ER+/PR- tumors." (PMID 24278290, 2013). "The cytoprotective and antioxidant genes, such as GPX1, CAT, and SOD2, are some examples of NRF2-regulated genes that could be implicated in tumor progression, metastasis, and resistance to chemotherapy." (PMID 40565143, 2025). "Furthermore, CD74 and GPX1 were found at higher levels in disseminated hybrids than in tumor-resident hybrids." (PMID 39421442, 2024). "We further verify that expression of three genes identified from our scRNA-seq analyses, thymosin beta 10 (TMSB10), CD74 and GPX1, are expressed at the protein level in hybrid cells within patient-matched primary tumor and peripheral blood (n = 4; n = 1 GEP class 1 and n = 3 GEP class 2)." (PMID 39030653, 2024).
tumor (continued). "In addition, fumarate can bind to and activate the ROS-scavenging enzyme GPX1 (glutathione peroxidase 1), promoting tumor cell growth and survival." (PMID 39438765, 2024). "This downregulation suggests a potential tumor-suppressive role for GPx1 in this neoplasia." (PMID 39594547, 2024). "Moreover, increased expression of GPx1 has been shown to suppress the malignant phenotype both in vivo and in vitro (51% and 39% tumor cell growth suppression compared to controls, respectively)." (PMID 39594547, 2024). "Notably, TMSB10 and GPX1 were significantly more expressed in disseminated hybrid cells compared to circulating tumor cells." (PMID 39421442, 2024). "However, the expression levels and prognostic values of GPX1 in different tumour types are still controversial according to different cohorts and statistical analyses." (PMID 37446063, 2023). "Previous researches had already revealed that the abnormally increased GPX1 activity could decrease tumor sensitivity toward ROS‐generating anticancer drugs." (PMID 37606338, 2023). "According to the current evidences, GPX1 acts as a tumor promoter in GC patients." (PMID 37862109, 2023). "The glutathione peroxidase-1 (GPX1) gene is also related to tumour proliferation in humans." (PMID 37299554, 2023). "Furthermore, we found that genetic polymorphism of the GPX1 antioxidant enzyme is associated with the phenotypic characteristics of UBC such as disease stage and tumor grade, i.e., with the aggressiveness of the disease." (PMID 36676755, 2023). "In addition, more disseminated hybrid cells expressed GPX1 than tumor-resident hybrids (p value = 0.007)." (PMID 38106024, 2023). "Namely, the GPX1 Pro198Leu and GPX1 Leu198Leu genotypes, which functionally have a lower activity compared to the GPX1 Pro198Pro genotype, were significantly more often detected in patients with a lower disease stage and a lower tumor grade." (PMID 36676755, 2023). "However, GPX1 genotypes distribution differed significantly according to the tumor stage (p ˂ 0.049) and pathohistological grade (p ˂ 0.018)." (PMID 36676755, 2023). "Taken together, GABPA was a tumor suppressor that inhibited migratory potential in GC through negatively regulating GPX1, which could be utilized in the clinical targeted therapy of GC." (PMID 36042907, 2022). "The mechanisms of how GPX1 exerts its tumor suppression effect need further research in KIPP." (PMID 34922551, 2021). "Similarly, the significant correlation between high expression levels of the GPX1 gene and the C4 and C6 subtypes suggest that these genes play a role as tumor promotors, since patients with these immune-cell subtypes have lower survival rates." (PMID 33706760, 2021). "Similarly, the overexpression of glutathione peroxidase 1 (GPx1), another hydrogen peroxide detoxifying enzyme, completely suppressed tumor cell growth in nude mice bearing v-Ha-ras-transformed rat kidney epithelial cells." (PMID 34680186, 2021). "This could explain the significant positive correlation between the GPX1 gene and stromal- and immune-cell scores in multiple tumor types." (PMID 33706760, 2021). "In sum, VPS9D1-AS1 exerted a tumor-facilitating function in ALL via a GPX1-mediated way." (PMID 32808668, 2020). "Moreover, high GPX1 levels were positively correlated with short overall survival time, distant metastasis, lymphatic metastasis, and tumor stage." (PMID 31844035, 2019). "In summary, GPX1 plays a different role in different tumor models." (PMID 31844035, 2019). "Association between GPX1 Pro198Leu polymorphism and tumor grade was not applicable because of the very limited number of cases in grades I and II." (PMID 29411539, 2018). "In summary, it was speculated that SELENBP1 inhibits GPX1 activity and thus may function as a tumor suppressor only by regulating GPX1." (PMID 29535818, 2018).
tumor (continued). "A search of the Oncomine database revealed 14 studies that compared the levels of GPX1 transcripts between normal prostate and tumor tissues, and none revealed a significant association." (PMID 30453672, 2018). "In addition, we also determined that the expression of the enzymes GLUT1, HK2, PKM2, and LDHA decreased in tumor tissue sections from the xenografts formed by GPx1 silencing in SW1990 cells." (PMID 30538220, 2018). "Scoring categories according to the percentages of GPx1 positive cells in the tumor." (PMID 28536671, 2017). "Scoring categories according to the intensity of GPx1 labeling in the tumor." (PMID 28536671, 2017). "Moreover, we observed a significant correlation between tumors expressing GPx1 and the tumor localization." (PMID 28536671, 2017). "Further cytological experiments corroborated that peptide-Au clusters are promising nanoparticles inducing tumor cells apoptosis by suppressing GPx-1 activity and increasing higher cellular reactive oxygen species level to initiate tumor cell apoptosis through intrinsic mitochondrial pathway." (PMID 28273930, 2017). "A total of 87 pretreatment patient tumor samples were stained for GPx1." (PMID 28536671, 2017). "GPx1 acts as a tumor suppressor gene via several potential mechanisms." (PMID 27023612, 2016). "As both, GPx1 down-regulation and GPx1 overexpression support tumor development, GPx1 could be responsible for the similar −Se and ++Se effect on tumor development in the WT." (PMID 23977205, 2013). "GPX1 expression in different locations of tumor cells may have a different impact on tumor development, which warrants further investigation." (PMID 24228025, 2013). "To determine if reducing ROS could preserve muscle morphology, we overexpressed ROS scavengers Catalase (Cat) and superoxide dismutase (Sod1), or antioxidative enzyme glutathione peroxidase 1 (GPx1, previously validated in), specifically in the muscles of tumour-bearing animals (QRasV12scribRNAi)." (PMID 38429578, 2024). "The overexpression of GPX1 could reduce the tumor growth in vivo and in vitro." (PMID 35712475, 2022). "The increased GPX1 activity in tumor cells may contribute to resistance to antitumor drug therapy." (PMID 35626163, 2022). "Importantly, we proved that VPS9D1-AS1 served as a tumor promoter in ALL through elevating GPX1." (PMID 32808668, 2020). "Also, significant differences were found between the GPx1 groups and different tumor sites." (PMID 28536671, 2017). "We analysed the changes in antioxidant (SOD1, SOD2, CAT, GPX1, HIF-1α, and NRF2) and anti-inflammatory nuclear factor kappa B (NF-κB) gene expression in tumour-bearing mice." (PMID 39506978, 2024). "Tumor sections were subjected to qRT‐PCR and immunohistochemical staining to analyze the expression of circMAP2K2, PCBP1 and GPX1 in the xenograft tumors." (PMID 37752765, 2023). "An even more pronounced effect of decreased tumor growth and increased animal survival was achieved in MIA PaCa-2 cells when SOD2 and GPX1 were overexpressed simultaneously." (PMID 36552527, 2022). "Subsequently, we established subcutaneous tumor xenografts in athymic nu/nu mice using stable MDA-MB-231 cells and administered Dox to the mice twice weekly to maintain GPx1 depletion." (PMID 34158609, 2021). "In CP-resistant NSCLC cells, glutathione peroxidase 1 (GPX1) remarkably diminishes ROS levels to stimulate Akt signaling, as a tumor-promoting factor for CP resistance." (PMID 33921908, 2021). "Just recently, when expression of GPX1 protein was evaluated in RCC, high GPX1 level was in a positive correlation with tumor stage, distant metastasis, lymphatic metastasis, and shorter overall survival." (PMID 33953831, 2021). "Suppression of GPX1 leads to elevation of extracellular hydrogen peroxide, which facilitates the conversion of normal fibroblast to CAF phenotype, and promotes the tumor-forming capacity and invasiveness." (PMID 31824853, 2019).
tumor (continued). "In summary, SELENBP1 influences the tumor microenvironment and SELENBP1 action is functionally influenced by GPX1." (PMID 29535818, 2018). "In this study, we found that GPx1/ROS/AMPK-mediated autophagy activation rescues PDA cells in response to the energy stress of glucose-free culture, which mimics the poor tumor microenvironment." (PMID 30538220, 2018). "Additionally, it was suggested that miR-21 influences the tumor microenvironment by modulating antioxidant enzymes like SOD2 and GPx1, as well as signaling suppressors SOCS1 and SOCS6, thereby promoting conditions favorable for tumor growth." (PMID 41465462, 2025). "SOD1, CAT, GPX1, and HIF-1α were significantly increased in the lungs of tumour-bearing mice." (PMID 39506978, 2024). "Both TMSB10 and GPX1 were expressed on significantly higher numbers of disseminated hybrid cells compared to circulating tumor cells, and CD74 and GPX1 were expressed on more disseminated hybrids than tumor-resident hybrids." (PMID 38106024, 2023). "In patient-matched tumor and peripheral blood, we verified gene expression by examining concordant protein expression for each pathway category: TMSB10 (cell motility), CD74 (immune evasion) and GPX1 (metabolism)." (PMID 38106024, 2023). "Decreases in Mn and Se levels may be related to the adaptive defense mechanism of tumor cells directly or through AOE (antioxidant enzyme), such as Mn-SOD and GPx1, to avoid increased apoptosis." (PMID 37446063, 2023). "Furthermore, we verified that hybrid cells within the primary tumor and in peripheral blood express TMSB10, CD74 and GPX1 at the protein level, and that TMSB10 and GPX1 are significantly upregulated in disseminated hybrid cells compared to CTCs." (PMID 38106024, 2023). "Moreover, the expression of Gpx-1 was related to the expression of proliferating cell nuclear antigen (PCNA) which is commonly present in proliferating cells and tumour cells." (PMID 37242524, 2023). "Serving as a tumor suppressor, GABPA blocks GC cells to migrate by targeting GPX1." (PMID 36042907, 2022). "Gpx1, a redox protective factor for FAK kinase, prevents kinase inactivation via H2O2, whereas Gpx1 deletion downregulates FAK/c-Src activation, thus preventing the spread and metastasis of tumor cells." (PMID 36407100, 2022). "The combined treatment of GPX1 inhibitors, including MSA or Pentathiepins, with photodynamic therapy can generate synergistic anticancer effects by enhancing oxidative stress, accumulating ROS, and inducing apoptosis in tumor cells." (PMID 35626163, 2022). "The TXNRD1, GPX1, and GPX2 genes may exert dual effects in tumor mutagenesis and development, while the TXNRD1, GPX1, GPX2, and GPX3 genes were found to be related to drug sensitivity or the formation of drug resistance." (PMID 33706760, 2021). "The observed reduction in Mn and Se levels in erythrocytes may be related to an adaptive defence mechanism of tumour cells either directly or through Mn-SOD and GPx1 to prevent OS-induced or caspase-induced apoptosis in epithelial ovarian cancer (EOC) from increasing." (PMID 37446063, 2023). "However, compared to that in non-malignant tissues, the expression level of GPx1 in tumor tissues was significantly decreased by 7.4%." (PMID 32571353, 2020).
infection (21 papers, 2010 to 2024). The state of being infected such as from the introduction of a foreign agent such as serum, vaccine, antigenic substance or organism. "Infection of cells with a lentiviral vector carrying the sequence of human GPX1 glutathione peroxidase protects against the toxic effects of 6-hydroxydopamine." (PMID 37891948, 2023). "In contrast, it was shown that the expression of GPX-1 exhibited a statistically significant increase at 15 days post-infection compared to the other time periods." (PMID 38275638, 2023). "We quantified the protein expression of NQO1, GPX1, Prdx1, HO-1, and HO-2 during the course of infection." (PMID 32669339, 2020). "In GPX1-overexpressing hUSLFs (MOI = 30) the GFP fluorescence positive rate which represents the cell infection rate was more than 80%." (PMID 28783735, 2017). "C57BL/6 mice (wild-type (WT) and GPx1 transgenic (GPxtg) were infected with T. cruzi and at 45 days post-infection (dpi), immunized with TcG2/TcG4 vaccine delivered by a DNA-prime/Protein-boost (D/P) approach." (PMID 26075398, 2015). "Interestingly, the expression of GPx-1 increased during the first 3 days of infection, but GPx-2 was downregulated during invasion." (PMID 37210527, 2023). "The GPx-1 gene exhibited a notable increase in expression at the 3 h mark following infection." (PMID 38275638, 2023). "In addition, infection of nigral neurons using the same GPX1-gene-containing vector led to small but significant protection against intrastriatal injection of 6-hydroxydopamine." (PMID 37891948, 2023). "GPx1 was shown to play a particular role in the pathogenicity of IV infection." (PMID 30049972, 2018). "Infection with C. concisus UNSWCD induced an oxidative stress response in IECs, with a range of metallothionein-encoding transcripts found to be upregulated, in addition to nitric oxide synthase 2 (NOS2) and glutathione peroxidase 1 (GPX1)." (PMID 27677841, 2016). "Downregulation of SelP in infection/acute phase reaction may represent a mechanism to generate Se for incorporation into other selenoproteins that are more directly involved in immunity e.g. GPx1, TrxR1 and Selenoprotein K." (PMID 30571741, 2018). "As a general trend, we observed a slight decrease in the expression of GPX1, GPX4, SELENOO and SELENOS at days 2, 3 or 4 post-infection." (PMID 35163318, 2022). "As the cellular enzyme, GPX-1, also functions in the detoxification of ROS, we also examined levels of GPX-1 protein during infection." (PMID 35215840, 2022). "The level of GPx1 in the thymus was lower than that of the control SPF chickens after REV infection, and showed significant changes on day 28 (P < 0.05) post-infection." (PMID 33308224, 2020). "IV infection can decrease the production of antioxidation targets, such as HO-1 and NQO1, SOD1, GR, CAT, and GPx1 are downstream molecules of the Nrf2 pathway after IV infection." (PMID 32689931, 2020). "The transcription level of most genes involved in GSH metabolism, including Gpx1, Ggt1, Gsr, Pgd, Anpep and Lap3, was significantly higher post-infection than pre-infection in the delta group but not in the omicron group." (PMID 39759510, 2024). "Consistent with a central role for oxidative stress responses in cell-intrinsic responses to infection, key antioxidant enzymes (GSR, CAT, GPX1, and PRDX1) were downregulated by YFV-17D and select genes (SOD2, NFE2L2, and KEAP1) were upregulated by MnTBAP treatment." (PMID 39282299, 2024). "The down-regulation of these genes in GPX-1 and GST-mu treated bacteria challenged L. rohita, suggesting that the external supply of these proteins might influence the endogenous synthesis of CuZnSOD, GPX-1 and GST-mu transcripts during the infection process." (PMID 38275638, 2023). "In mice lacking H2O2-scavenging enzyme, GPx1, IV infection results in a more severe and longer BALF inflammation as compared to their wild type littermates." (PMID 30049972, 2018).
infection (continued). "Interestingly, our microarray data showed that the expression level of BEX2, GLRX3, GPX1 and PXCARD were down-regulated at 4 days post-infection, which is different from the up-regulated mRNA level at 8 hours post infection." (PMID 21172007, 2010). "A large number of genes involved in detoxifying reactive oxygen species (ROS) and superoxide radicals (sod, cat, ahp, bcp, gpx1, trx) were also expressed in the non-suppressive rhizosphere samples most likely in response to the infection of wheat roots by R. solani AG8." (PMID 29780371, 2018). "By comparing iPA-mediated effects in the two cited cell lines, we observed that iPA strikingly increased the expression of GPX1 and TR1 in CuFi-1 cells characterized by an intrinsic inflammation also in the absence of any infection." (PMID 29230506, 2018).